AQP3 (aquaporin 3 (Gill blood group))
Diseases named in the same sentence as AQP3 in open-access papers (continued):
Sharing a sentence is not in itself a finding about the gene and the disease.
Dry skin (8 papers, 2020 to 2024). Skin characterized by the lack of natural or normal moisture. "Reduced AQP-3 expression is known to cause dry skin, as demonstrated by AQP3 knockout mice exhibiting dry skin and impaired wound healing." (PMID 39273607, 2024). "Decreased AQP3 levels with aging might also underlie another common issue observed in aged skin: skin dryness (xerosis) and impaired permeability barrier repair following disruption." (PMID 37997995, 2023). "Moreover, skin disorders such as dry skin caused by epidermal growth factor receptor inhibitor administration may also be associated with decreased skin expression of AQP3." (PMID 34205315, 2021). "The most common mucocutaneous side effects of isotretinoin therapy, dry skin, have been related to increased expression of keratinocyte aquaporin 3 (AQP3), which damages the skin barrier and enhances transepidermal water loss causing skin dryness." (PMID 36585988, 2023). "AQP3 is an important protein that regulates keratinocyte proliferation, differentiation, and migration, as well as skin hydration and water permeability repair in vivo, and dysregulation of AQP3 leads to impaired wound healing and xerosis." (PMID 36674890, 2023). "In the future, development of adhesive plasters and cosmetics containing Kumazasa extract that have AQP3-increasing effects can be expected to support new strategies for wound healing and alleviation of dry skin." (PMID 34205315, 2021). "Therefore, substances that increase AQP3 expression by signaling pathways other than Ras/MAPK or substances that activate the Ras/MAPK pathway in a skin-specific manner would be effective for treatment or preventing erlotinib-induced dry skin." (PMID 32260143, 2020). "Therefore, substances that increase AQP3 expression may be effective for erlotinib-induced dry skin." (PMID 32260143, 2020). "In addition, gefitinib-induced dry skin may also be attributable to decreased AQP3 in the skin." (PMID 32260143, 2020). "The functions of these AQP family members in the skin are poorly understood, and their expression levels were significantly lower than that of AQP3; therefore, we believe that they are unlikely to be involved in erlotinib-induced dry skin." (PMID 32260143, 2020).
inflammatory bowel disease (8 papers, 2016 to 2025). A spectrum of small and large bowel inflammatory diseases of unknown etiology. "Growing evidence indicates that the expression or alteration of AQP3 in the intestine may be associated with a variety of intestinal disorders, including inflammatory bowel disease, diarrhea, intestinal barrier injury, irritable bowel syndrome, intestinal oxidative stress and autophagy." (PMID 40661958, 2025). "Increasing data has indicated that the expression or alterations of AQP3 in the gut may be associated with several intestinal disorders, such as inflammatory bowel disease, diarrhea, intestinal barrier injury, irritable bowel syndrome, intestinal oxidative stress, and autophagy." (PMID 38089478, 2023). "Previous studies showed that the expression of AQP1, AQP3, AQP7 and AQP8 in patients with inflammatory bowel disease was significantly decreased, whereas the expression of AQP3 was significantly increased in the process of magnesium phosphate-induced diarrhea." (PMID 35458572, 2022). "Previous studies have shown that AQP3 is down-regulated during inflammatory bowel disease in humans and rats." (PMID 29373601, 2018). "In conclusion, current studies suggest that AQP3 may act as an important target for disorders that involve disruption of intestinal fluid homeostasis like diarrhea, constipation, inflammatory bowel disease and irritable bowel syndrome." (PMID 40661958, 2025). "For example, the AQP3 mRNA was detected in the distal ileum and colon while the localization of AQP3 protein was confirmed at the intestinal mucosal epithelium of patients with inflammatory bowel diseases by immunofluorescence confocal microscopy (Ricanek al., 2015)." (PMID 38089478, 2023). "The downregulation of AQP3 and AQP8 was accompanied by an increase in intestinal inflammation and injury, suggesting that both AQP3 and AQP8 may be involved in the pathogenesis of inflammatory bowel disease." (PMID 33673336, 2021). "The reduced mRNA expression of several AQPs (AQP1, AQP3, AQP7 and AQP8) in human intestinal mucosa has been demonstrated at the early stage of inflammatory bowel diseases (IBD), including Crohn’s disease and ulcerative colitis." (PMID 27589719, 2016).
vitiligo (8 papers, 2019 to 2025). Generalized well circumscribed patches of leukoderma that are generally distributed over symmetric body locations and is due to autoimmune destruction of melanocytes. "Recent experimental findings on whether systemic AQP3 deficiency causes vitiligo suggest that both systemic and localized AQP3 deficiency exists in vitiligo and correlates with disease severity and oxidative stress." (PMID 36532729, 2022). "Furthermore, keratinocyte‐specific oxidative stress, evidenced by reduced AQP3 expression, directly induces melanocyte apoptosis in vitiligo." (PMID 40856249, 2025).
asthma (7 papers, 2016 to 2024). "In a murine model of ovalbumin-induced asthma, AQP3 associates with chemokine production (CCL24 and CCL22) in alveolar macrophages and with the transmigration of T cells." (PMID 39125952, 2024). "It is therefore proposed that the up-regulation of AQP3 expression is intricately linked to the accumulation of inflammatory cells in asthma." (PMID 39440058, 2024). "Thus, the loss of AQP3 resulted in reduced OVA-induced asthma responses, resulting in less eosinophilic inflammation and decreased Th2 cytokine production." (PMID 27165276, 2016). "We tested this hypothesis using AQP3 deficient (AQP3−/−) mice in an ovalbumin (OVA)-induced murine asthma model." (PMID 27165276, 2016). "In asthma, where chronic inflammation of the airways is triggered by factors including oxidative stress, AQP3 peroxiporin activity is thought to be pivotal in the initiation of the inflammatory process." (PMID 39125952, 2024). "Ovalbumin (OVA)-induced asthma in AQP3-knockout mice resulted in significantly reduced airway inflammation compared with OVA-induced asthma in wild-type mice." (PMID 32824013, 2020). "Further, we found that, compared to WT AMs, the genes in the M2 marker were less upregulated in AQP3−/− AMs in an in vivo asthma model, but, conversely, they were more upregulated by in vitro stimulation with IL-4/13." (PMID 27165276, 2016). "Further, we then determined that AQP3 facilitated murine asthma through mediating chemokine production from alveolar macrophages (AMs) as well as regulating T cell trafficking." (PMID 27165276, 2016). "Here we report that AQP3 potentiates ovalbumin (OVA)-induced murine asthma by mediating both chemokine production from alveolar macrophages and T cell trafficking." (PMID 27165276, 2016). "As T cells, especially CD4+ T cells, play a critical role in the pathogenesis of asthma, we focused on AQP3 expression in those cells." (PMID 27165276, 2016). "To determine the role of AQP3 in functions of AMs during OVA-induced asthma, using microarray analysis we compared the gene expression profiles of AMs in WT and AQP3−/− mice before and after OVA challenge." (PMID 27165276, 2016). "Our results suggest that AQP3 potentiates asthma through mediating T cell trafficking and chemokine production from M2 polarized AMs by regulating the amount of cellular H2O2." (PMID 27165276, 2016). "For instance, AQP3 was reported to potentiate ovalbumin-induced asthma." (PMID 36246134, 2022). "We hypothesized that AQP3 would contribute to the pathogenesis of asthma by regulating the amount of cellular H2O2." (PMID 27165276, 2016). "Here we have revealed a critical role of AQP3 in OVA-induced asthma." (PMID 27165276, 2016). "Thus, AQP3 may mediate asthma partly through regulating the production of chemokines and tissue repair-related factors from AMs." (PMID 27165276, 2016). "Thus, AQP3 may represent a new therapeutic target for the treatment of allergic disorders overall, including asthma." (PMID 27165276, 2016). "Asthma models based on ovalbumin instillation exhibit changes in expression levels of AQP1, AQP3, AQP4, and AQP5." (PMID 30397774, 2019). "Another study on ovalbumin-induced asthma models also reported reduced mRNA levels for AQP1, AQP4, and AQP5 but elevated AQP3 mRNA levels." (PMID 30397774, 2019). "Therefore, AQP3 may be a novel and interesting therapeutic target for severe asthma." (PMID 27165276, 2016). "Thus, we consider that AQP3 may not directly contribute to OVA-induced asthma through its expression on epithelium or B cells although further investigation is needed." (PMID 27165276, 2016).
lymph node metastasis (7 papers, 2014 to 2024). "In particular, AQP3 and E-cadherin were associated with lymph node metastasis, while AQP3 and vimentin were associated with Lauren classification, and E-cadherin was associated with depth of tumor invasion." (PMID 24887009, 2014). "Elevated AQP3 expression in cancer tissues was associated with Lauren classification, lymph node metastasis, and lymphovascular invasion (P < 0.05)." (PMID 24887009, 2014). "Additionally, AQP3 expression was associated with histological classification, lymph node metastasis, and lymphovascular invasion, indicating the involvement of AQP3 in the carcinogenesis and progression of GC." (PMID 24887009, 2014). "In cases with low levels of differentiation, lymph node metastasis and distant metastasis, AQP3 expression was significantly higher than that observed in cases with high levels of differentiation, no lymph node metastasis and no distant metastasis." (PMID 32662230, 2020). "Clinical stage, tumor diameter, lymph node metastasis, tumor infiltration depth, serum SCC-Ag level, HPV infection status, treatment protocol, and expression of AQP1 and AQP3 were associated with cumulate survival rate in cervical cancer." (PMID 24918928, 2014). "AQP3 was associated with TNM stages and lymph node metastasis of LUAD patients." (PMID 39060229, 2024). "Expression of AQP3 and that of CD44 positively correlated with Lauren classification, lymph node metastasis, and lymphovascular invasion." (PMID 26918728, 2016).
bladder cancer (6 papers, 2013 to 2022). "Conversely, in patients with urothelial or bladder carcinomas, high levels of AQP3 protein and RNA were associated with better progression-free survival, suggesting that the roles of AQP classes are likely to depend on the cancer subtype." (PMID 32679804, 2020). "In a study of 94 patients with bladder carcinoma, high tumor stage was associated with decreased levels of AQP3 expression." (PMID 28991174, 2017). "In humans, polymorphisms in AQP3 have recently been related to increased bladder cancer risk in individuals from New Hampshire who were exposed to arsenic in drinking water." (PMID 23322787, 2013). "The expression of AQP1 and AQP3 in bladder cancer tissue was measured by immunohistochemistry and RT-PCR." (PMID 36532729, 2022). "Similar to our findings, AQP3 levels were decreased in a cisplatin-resistant bladder cancer cell line compared to the parental cells." (PMID 26799320, 2016). "The results showed that Polyporus could significantly downregulate the relative expression of AQP1 and AQP3 mRNA in bladder cancer tissue of rats, indicating that the anti-bladder cancer effect may be produced by regulating AQP1 and AQP3 in bladder cancer tissue." (PMID 36532729, 2022). "It is not known why AQP3 seems to be decreased in bladder cancer, but is overexpressed in multiple other cancers." (PMID 28991174, 2017).
gastric adenocarcinoma (6 papers, 2012 to 2024). "The gene signature consisting of the NDUFA4L2, ANKRD45, and AQP3 genes is a promising biomarker to distinguish the prognosis, the molecular and immune characteristics, the depressive risk, and the therapy candidates for gastric adenocarcinoma patients." (PMID 39409106, 2024). "The relationship between NDUFA4L2, ANKRD45, and AQP3 with the clinicopathologic characteristics of gastric adenocarcinoma was presented with the heatmap." (PMID 39409106, 2024). "A recent study has suggested that AQP3 is involved in Helicobacter pylori infection-related gastric carcinogenesis since AQP3 expression was upregulated both in human gastric adenocarcinoma cells and in rat gastric tissues." (PMID 27589719, 2016). "The signature based on the NDUFA4L2, ANKRD45, and AQP3 genes was evaluated with the area under curve (AUC) and nomogram-predicted probability, and the signature showed an ideal value to predict the OS of gastric adenocarcinoma." (PMID 39409106, 2024). "AQP3 was downregulated in the gastric adenocarcinoma and was positively correlated with the OS." (PMID 39409106, 2024). "AQP-3 and AQP-5 promote migration and proliferation of gastric adenocarcinoma cells." (PMID 33209198, 2020).
triple-negative breast carcinoma (6 papers, 2021 to 2025). An invasive breast carcinoma which is negative for expression of estrogen receptor (ER), progesterone receptor (PR), and human epidermal growth factor receptor 2 (HER2). "High protein expression of AQP1, AQP3 (triple-negative breast cancer) and AQP5 (early and triple-negative breast cancer) revealed a correlation with spread to lymph nodes and poor prognosis." (PMID 37681917, 2023). "In triple negative breast cancer cells MDA-MB-231, AQP3 inhibition by shRNA decreased cellular water and glycerol permeability, cell proliferation, migration, and invasion." (PMID 36212456, 2022). "In triple-negative breast cancer (TNBC) patients, markedly higher expression of AQP5 and AQP3 was observed in cancer tissue than in adjacent normal tissue." (PMID 33947079, 2021). "Interestingly, MCF10A did not react to either of the treatments nor to AQP3 silencing with changes in the PI3K/Akt pathway, which is in line with previously published data using an Akt inhibitor, which affected viability of triple-negative breast cancer cell lines, but not MCF10A." (PMID 37175840, 2023).
eczema (5 papers, 2010 to 2025). "AQP3 was found to be the predominant aquaporin in human skin which increased expression and altered cellular distribution of AQP3 in eczema thus contributing to water loss." (PMID 20805891, 2010). "Increased expression and altered cellular distribution of AQP3 have been found in eczema, which may contribute to water loss." (PMID 38138183, 2023). "The increased expression and altered cellular distribution of AQP3 found in eczema may contribute to water loss." (PMID 28170435, 2017). "Increasing the expression of AQP3 in local lesions may inhibit eczema inflammation." (PMID 34721653, 2021).
gastritis (5 papers, 2015 to 2023). Inflammation of the stomach. "Specifically, AQP3 mRNA has been observed in patients with chronic atrophic and chronic superficial gastritis." (PMID 39128069, 2023). "A significantly higher expression of gastric mucosal AQP3 was detected in patients with chronic superficial gastritis compared with patients with chronic atrophic gastritis." (PMID 27589719, 2016). "Furthermore, an up-regulation of AQP3 was observed under chronic inflammatory conditions such as present in periodontitis and gastritis." (PMID 27824951, 2016). "For example, AQP3 mRNA is expressed in chronic atrophic and chronic superficial gastritis patients." (PMID 27589719, 2016). "Collectively, these results indicate that the expression of several subtypes of AQPs (AQP1, AQP3, AQP4, AQP5, AQP7 and AQP11) is upregulated by gastritis, and more studies are essential to investigate their potentials as diagnostic biomarkers and drug targets for gastritis therapy." (PMID 27589719, 2016). "For example, there is a relationship between the altered human AQP3 and AQP4 mRNA expression and gastritis types." (PMID 30336596, 2018). "In addition, a correlation between AQP3/AQP4 expression and gastritis types was proposed." (PMID 27589719, 2016).
Hyperglycemia (5 papers, 2013 to 2023). An increased concentration of glucose in the blood. "AQP3 and AQP7 have been described to modulate glycerol efflux from adipose tissue, thus controlling the glycerol influx into hepatocytes, via AQP9 to prevent the excessive lipid accumulation and the subsequent aggravation of hyperglycemia." (PMID 33465153, 2021). "Finally, it was recently shown that down-regulation of AQP3 in STZ-induced diabetic mice was not the result of hyperglycemia per se, since one week after STZ injection, serum glucose levels were increased without an accompanying reduction in AQP3 expression." (PMID 36674890, 2023).
liver cancer (5 papers, 2019 to 2025). An epithelial or non-epithelial malignant neoplasm that arises from the liver. "AQP3 is the aquaglyceroporin most associated with tumor progression, being overexpressed in different types of cancer such as skin, lung, colon, pancreatic and liver cancer." (PMID 39941100, 2025). "AQP3 plays a critical role in liver cancer chemoresistance by enhancing autophagy through multiple mechanisms." (PMID 40161518, 2025). "Dramatic increases in patient risk were observed for AQP3 in esophageal cancer (HR18.4), and AQP9 in liver cancer (HR 10.8)." (PMID 32679804, 2020). "Compared with the normal liver cell line L02, Huh7, and HCCLM3 cells showed maximal AQP3 expression among the seven liver cancer cell lines." (PMID 31197130, 2019). "The study also found an upregulation of AQP9 and a downregulation of AQP3 (two molecules belonging to the same family of AQP7), indicating that the dysregulation of the aquaporine activity could play a fundamental role in the liver cancer development and progression." (PMID 31757200, 2019).
malaria (5 papers, 2018 to 2023). Malaria is a serious and sometimes fatal disease caused by a parasite that commonly infects a certain type of mosquito which feeds on humans. "The identification of AQP3 and other potential host factors that are differentially regulated throughout the liver stage of malaria has implications for understanding host-parasite interactions." (PMID 29775485, 2018). "Furthermore, AQP3 is required by both P. vivax and P. falciparum for their development during blood stages, therefore, AQP3 inhibitors may contribute to pan anti-malaria activity." (PMID 36685595, 2022). "Therefore, the development of AQP3 inhibitors may have an anti-hypnozoite effect which may decrease the prevalence of relapsing malaria." (PMID 36685595, 2022). "Another possible target for HDT development in malaria, which is involved in the transport of water, glycerol and H2O2 through cell membranes, is the transmembrane channel aquaporin-3 (AQP3)." (PMID 35669122, 2022). "Auphen, an inhibitor of AQP3 that localize in the PVM between the host cell and the Plasmodium parasite reduces P. vivax liver hypnozoite and schizont burden, and inhibits P. vivax asexual blood-stage growth, and thus suggest that the AQP3 may be targeted for malaria treatment." (PMID 33796134, 2021).